TRIB1 (tribbles pseudokinase 1)
Diseases named in the same sentence as TRIB1 in open-access papers (continued):
Sharing a sentence is not in itself a finding about the gene and the disease.
cancer (continued). "Altogether, these interactions emphasize that TRIB1 is at the center of major cell signaling pathways, suggesting a role as a precise mediator of cellular homeostasis as well as different cancers and immune disorders." (PMID 35205759, 2022). "In non-small lung cancer cells, cisplatin treatment resulted in the enrichment of multidrug-resistant cancer stem cells, which overexpress TRIB1." (PMID 34205360, 2021). "The apparent role of TRIB1 in a range of important cellular processes, across cancer types, highlights the need for further investigation of TRIB1 in solid tumours." (PMID 34205360, 2021). "TRIB1 is emerging as a critical player in both tumour development and treatment resistance across a variety of cancers." (PMID 34205360, 2021). "Further research is required to fully realise the potential of TRIB1 as either a direct target of small-molecule drugs or a biomarker of treatment response across diverse cancer types." (PMID 34205360, 2021). "By reviewing the biological significance of TRIB1 in cancer, immunity, and lipid metabolism, this paper discusses the role of TRIB1 in the development of diseases and proposes new strategies for disease treatment." (PMID 34539875, 2021). "Of the four Tribbles proteins, TRIB1 has been most well characterised structurally and plays roles in diverse cancer types." (PMID 34205360, 2021). "The association of increased TRIB1 expression with treatment resistance, and decreased TRIB1 with sensitisation to treatment, across cancer types reiterates the importance of TRIB1 in oncogenesis and therapy in a range of contexts." (PMID 34205360, 2021). "While the regulation of retinoic acid signalling has implications across cancer types, the putative role of TRIB1 in ATRA resistance is particularly relevant in AML and APL, where ATRA is commonly used to drive cell differentiation as part of treatment." (PMID 34205360, 2021). "This suggests that TRIB1 can be used as a potential therapeutic target and general marker of cancer." (PMID 34539875, 2021). "Next, we performed a transient transfection of PC3 cells with TRIB1 siRNA/scramble and miR-132-3p mimic/control and analyzed the gene expression profile of pro-inflammatory cytokines and cancer-related genes and found similar signatures." (PMID 33329538, 2020). "TRIB1 has been implicated in the pathogenesis of various diseases including cancer, and the regulation of TRIB1 stability and levels remains a subject of controversy." (PMID 29176948, 2017). "Therefore, inhibiting TRIB1 can be considered a potential strategy for targeted cancer therapy that would alter the function/activity of important proteins such as Akt and MAPK in normal cells." (PMID 38791967, 2024). "Tribbles pseudokinase 1 (TRIB1) is a pro-cancer gene involved in cancer initiation and progression, which could be used as a biomarker for the diagnosis and prognosis of diseases." (PMID 39376611, 2024). "Curiously, Trib1 appears to be able to support cell proliferation in human cancers." (PMID 37355685, 2023). "Additional studies are needed to fully understand the transcriptional processing of TRIB1 gene and how it may be regulated in different cancer types." (PMID 37528172, 2023). "Tribbles pseudokinases (TRIB1-3) are important signaling modulators involved in several cancers." (PMID 38254916, 2023). "It is currently unknown how Trib1 can differentiate between physiological (e.g., regeneration) and pathological (e.g., cancer) cell proliferation." (PMID 37355685, 2023).
cancer (continued). "This 8q24 locus is a well-known amplicon that is amplified in several cancer types; there is strong potential that TRIB1 is coamplified in this region, which could account for many of the implications of TRIB1 in several cancer types." (PMID 35205759, 2022). "Thus, TRIB1 appears as a potential therapeutic target for various cancers, immune and metabolic diseases." (PMID 35205759, 2022). "Whilst TRIB1 is oncogenic in several cancer settings, its potential importance in BC pathogenesis and response to therapy are largely unknown." (PMID 35664073, 2022). "The knockdown of TRIB1 resulted in the downregulation of the key cancer stem cell promoting transcription factors and the resensitisation of the cancer stem cells to cisplatin, confirming the importance of elevated TRIB1 expression in the development of the drug-resistant cancer stem cells." (PMID 34205360, 2021). "Here we review the structure–function relationship of TRIB1 in cancers." (PMID 34205360, 2021). "A broad-reaching mechanism for TRIB1 overexpression could be the location of TRIB1 within the common cancer amplicon 8q24, which also contains the oncogene c-MYC." (PMID 34205360, 2021). "While all Tribbles proteins have cancer-specific roles, we focus on TRIB1 for two reasons." (PMID 34205360, 2021). "In the context of various levels of TRIB1 expression in different solid tumour types, more systematic studies will be required to establish which subclasses of cancer TRIB1 levels could potentially aid prognosis." (PMID 34205360, 2021). "At the same time, TRIB1 has been reported to be upregulated in this cancer." (PMID 33329538, 2020). "TRIB1 expression was upregulated in tumors when compared to adjacent cancer-free tissue but was not allele specific." (PMID 30337939, 2018). "The contribution of Tribbles isoforms in mammals to insulin regulation and cancer is complex: recently, TRIB2 has been shown to be an Akt agonist, and an R107L mutation in TRIB1 that aligns with R141Q in TRIB3 promotes leukemogenesis by enhancing ERK phosphorylation and C/EBPα degradation." (PMID 29025897, 2017). "It is reported that Trib1 plays an important role in cancer cell activities." (PMID 26521947, 2015). "Finally, treatment of MDMs with cancer cell-conditioned medium (CM) also showed a significant overexpression of TRIB1 in these cells (MCM), compared to control (MUN) and MLPS+INF-γ cells (p < 0.05), suggesting a potential two-way regulation of TRIB1 expression between BC cells and tumor macrophages." (PMID 35664073, 2022). "Cancer amplification notwithstanding, a moderate increase in TRIB1 may indeed be beneficial." (PMID 27019349, 2016). "The Tribbles (TRIB) protein family, consisting of TRIB1, TRIB2, and TRIB3, has been shown to participate in cancer-related processes and plays a regulatory role in activating oncogenic signaling pathways such as the MAPK and PI3K-AKT pathways." (PMID 40958880, 2025). "TRIB1, TRIB2, and TRIB3 have been involved in different cancers including hematological malignancies (mostly TRIB2) and a variety of solid tumors." (PMID 38254916, 2023). "Of interest, TRIB1 knockdown in MDMs (MTRIB1-KD) enhanced expression of IL1β and TNF mRNA, emphasizing that cancer cell secreted factors that were used to re-educate MTRIB1-KD to TAMTRIB1-KD are effectively altering the phenotypes of these cells." (PMID 35664073, 2022). "Along with TRIB1, the TRIB protein family members TRIB2 and TRIB3 have attracted interest in terms of understanding their functional roles in diseases, mostly cancer and metabolic diseases." (PMID 35205759, 2022). "The selection for the co-amplification of TRIB1 and c-MYC, across cancer types, suggests dependency between the two genes." (PMID 34205360, 2021). "TRIB1 regulation of AKT1 and NF-κB seems likely to have a substantial impact on a variety of cellular processes across a range of cell and cancer types, though further investigation is required to understand the mechanism." (PMID 34205360, 2021).
cancer (continued). "TRIB1 and HDACs play crucial roles in cisplatin-induced enrichment of cancer stem cells (CSCs) and drug resistance in NSCLC, and patients with high levels of TRIB1 had a significantly poorer response to cisplatin and a poorer prognosis." (PMID 33867871, 2021). "The mRNA expression of TRIB1 was significantly upregulated in PC3 and LNCAP cells, compared to RWPE1, non-cancer prostate epithelial cells." (PMID 33329538, 2020). "This is consistent with the data obtained in human concerning TRIB1 in blood T-cells, for TRIB2 in LT7 cancer cells and for TRIB3 in Muller cells." (PMID 24834131, 2014). "The TRIB1 gene is located on chromosome 8q24.13, near c-MYC, and is amplified in cancer." (PMID 40958880, 2025). "TRIB1, which is located on chromosome 8q24, has been reported to contribute in many kinds of cancers, but its role in CRC has not been described." (PMID 28624785, 2017). "TRIB1 is also a known regulator of the mitogen-activated protein kinase (MAPK) pathway, which activates/inhibits key cell processes such as growth, proliferation, differentiation, migration, and apoptosis, all of which have a pivotal role in cancer development and progression." (PMID 30337939, 2018). "Therefore, TRIB1 overexpression seems to be characteristic to certain cancer subtypes and may not be used as a general marker of cancer." (PMID 34539875, 2021). "Thus, our data and the literature collectively suggest an important regulatory role for TRIB1 both in macrophages and tumour cells, thus may provide a novel mechanism for the interplay between the tumour microenvironment and cancer cells." (PMID 33329538, 2020).
tumor (28 papers, 2016 to 2025). "TRIB1 negatively regulates the anti-tumor cytokine IL-15 in TAMs in breast tumors, causing a decrease in T-cells that promote anti-tumor responses." (PMID 38791967, 2024). "Myeloid Trib1 deficiency led to an early acceleration of tumor growth, paired with a selective reduction in perivascular macrophage numbers in vivo and enhanced oncogenic cytokine expression in vitro." (PMID 35664073, 2022). "Trib1 and Trib2 are also implicated as tumor suppressors in some subtypes of AML through inhibition of JNK signaling." (PMID 27191957, 2016). "CD44, ETS2, RHOH, and TRIB1 also affect the proliferation and invasion ability of tumor cells by regulating the expression of downstream genes." (PMID 39684426, 2024). "Its close proximity to MYC and its involvement in fundamental pathways such as MAPK signaling, NF-кB signaling, and the PI3K-Akt pathway have led to the identification of TRIB1 as an oncogene that plays a pivotal role in tumor progression and maintenance." (PMID 38791967, 2024). "Tumors with wild type TRIB1 overexpression had higher tumor volume at day 17 post injection compared to EV or TRIB1-W337A tumors." (PMID 37528172, 2023). "Data mining of the TCGA dataset revealed that chromosomal instability (CIN) tumors have lower TRIB2 and higher TRIB3 expression versus microsatellite instability (MSI)-high tumors, while TRIB1 levels are similar in both tumor types." (PMID 38254916, 2023). "We also observed that one of the empty vector tumors had increased tumor volume comparable to TRIB1 tumors therefore it was excluded from significance testing." (PMID 37528172, 2023). "Our in vivo studies showed that mice bearing TRIB1 overexpressing tumors generated from patient derived primary GBM cell lines had increased tumor volume and shorter OS compared to mice with empty vector control tumors." (PMID 37528172, 2023). "This analysis revealed that up-to 25% of cells in the tumor expressed high levels of TRIB1 protein and that about 42% of these cells were also positive for the macrophage marker CD68." (PMID 35664073, 2022). "Given the data we present in this study, we propose that dysregulated levels of TRIB1 in myeloid cells leads to accelerated tumor growth via distinct molecular mechanisms." (PMID 35664073, 2022). "The authors experimentally validated the data by western blotting and found that the levels of TRIB1 protein were elevated in 6 out of 8 (75%) CRC tumors when compared to matched adjacent non-tumor tissue." (PMID 34198908, 2021). "The mechanism linking TRIB1 to JAK/STAT activity in tumour cells has yet to be identified, though further investigation is warranted." (PMID 34205360, 2021). "In conclusion, our study suggested that miR-513b-5p inhibited the expression of TRIB1 and exerted a tumor suppressor gene in Weri-RB1 cells." (PMID 34589612, 2021). "The results in this cell line are consistent with a recent report, and suggest that TRIB1 expression in PCa cells is inconsequential for tumor biology in the cell lines and conditions employed." (PMID 32932846, 2020). "We further corroborated that TRIB1 amplification is frequent in other tumor types, as illustrated by the analysis of TCGA datasets." (PMID 32932846, 2020). "We also found hypomethylation of TRIB1 in male patients along with over-expression, a gene that promotes tumor growth by suppressing apoptosis." (PMID 30616686, 2019). "Among them, TRIB1, an autosome gene, has been shown to promote tumor growth by suppressing apoptosis." (PMID 30616686, 2019). "High expression of TRIB1 has been shown to activate the NFκB pathway, which suppresses apoptosis, and leads to a clinically more aggressive tumor phenotype." (PMID 30616686, 2019).
tumor (continued). "An in vivo HCC tumor model was generated by implantation of HepG2 cells with stable TRIB1 knockdown into nude mice." (PMID 29176948, 2017). "The results showed that 6 out of 8 (75%) CRC tissues had elevated TRIB1 expression, when compared with paired non-tumor tissues." (PMID 28624785, 2017). "Assessment of tumor volume at the indicated time points showed that TRIB1 silencing significantly inhibited tumor growth." (PMID 29176948, 2017). "Furthermore, our in vivo results showed that mice bearing TRIB1-W337A tumors had lower tumor volumes and longer OS compared to those with wild type TRIB1 overexpressing tumors and empty vector control tumors." (PMID 37528172, 2023). "The regulatory role of TRIB1 as a pseudokinase protein in tumor development is extremely important." (PMID 34539875, 2021). "Moreover, we demonstrate that TRIB1 amplification and overexpression are frequent in this tumor type." (PMID 32932846, 2020). "To acquire further insight about the tumor-promoting function of TRIB1 in cellular system, we took advantage of our low TRIB1-expressing DU145 cells in which we could activate the expression of ectopic TRIB1 through the use of doxycycline." (PMID 32932846, 2020). "The biological insights on TRIB1 tumor-promoting activities are scarce." (PMID 32932846, 2020). "TRIB1, a member of the Trib family of serine/threonine kinase-like proteins, supports prostate tumorigenesis, and, in a xenograft model of human PC, TRIB1 depletion strongly inhibited tumor formation." (PMID 29562723, 2018). "Whilst it is to be formally tested in future studies, we speculate that TRIB1 expression changes in TAMs could be associated with the initiation and/or with the growth of the tumor and adaptation to lack of nutrients, as well as to hypoxic environment." (PMID 35664073, 2022). "In order to identify mTrib1-dependent mechanisms that may explain an impaired T-cell recruitment to the tumor, we have assessed the correlation between TRIB1 levels and genes that have been shown to regulate T-cell recruitment in the Cardiogenics Transcriptomic Study 31-33." (PMID 35664073, 2022). "Our observations presented above may link high TRIB1 levels mechanistically to the enhanced responses to anthracycline-based chemotherapy, prompting us to characterize how altered Trib1 expression in myeloid cells may alter BC tumor growth." (PMID 35664073, 2022). "Notably, IL-10 (p < 0.01), PD-L1 (p < 0.0001) and VEGF (p < 0.05) expression were significantly increased in TAMTRIB1-KD compared to MTRIB1-KD, suggesting the myeloid TRIB1 is an important regulator of oncogenic cytokine expression in TAMs, downstream of signals secreted by tumor cells." (PMID 35664073, 2022).